STAB1 (stabilin 1)
Description:
Acts as a scavenger receptor for acetylated low density lipoprotein. Binds to both Gram-positive and Gram-negative bacteria and may play a role in defense against bacterial infection. When inhibited in endothelial tube formation assays, there is a marked decrease in cell-cell interactions, suggesting a role in angiogenesis. Involved in the delivery of newly synthesized CHID1/SI-CLP from the biosynthetic compartment to the endosomal/lysosomal system.
Synonyms: FEEL-1; FEEL1; KIAA0246; STAB-1; CLEVER-1; FELE-1; FEX1; SCARH2; HRFT
Tractability: Antibody: its Gene Ontology location is reachable by antibodies, with high confidence; UniProt predicts a signal peptide or a membrane-spanning region; the Human Protein Atlas places it where antibodies can reach. PROTAC: its protein half-life has been measured.
Gene: Protein-coding gene on chromosome 3 (52,495,337 to 52,524,512, forward strand). Ensembl gene ENSG00000010327.
Subcellular location: Membrane
Subcellular location (Human Protein Atlas): Cytosol; Nucleoplasm; Plasma membrane
Pathways (Reactome):
Vesicle-mediated transport: Scavenging by Class H Receptors
Gene Ontology:
Molecular function: low-density lipoprotein particle binding; low-density lipoprotein particle receptor activity; protein binding; scavenger receptor activity; protein-disulfide reductase activity; calcium ion binding; hyaluronic acid binding
Biological process: cell-cell signaling; defense response to bacterium; negative regulation of angiogenesis; cell adhesion; receptor-mediated endocytosis; endocytosis
Cellular component: plasma membrane; endocytic vesicle membrane; membrane
Genetic constraint (gnomAD): Loss-of-function variants: 250 observed, 329.4 expected, observed/expected ratio (o/e) 0.76, 90% interval 0.68 to 0.84. The upper end of that interval is the gene's LOEUF score, 0.84, which puts it in group 3 of 6, group 1 being the genes least tolerant of losing a copy. Missense variants: 3,249 observed, 3,504.3 expected, observed/expected ratio (o/e) 0.93, 90% interval 0.9 to 0.95. Synonymous variants: 1,475 observed, 1,403.7 expected, observed/expected ratio (o/e) 1.05, 90% interval 1.01 to 1.1.
Homologues: Orthologues: chimpanzee STAB1 (99% identical), macaque STAB1 (97% identical), dog STAB1 (85% identical), guinea pig STAB1 (82% identical), rabbit STAB1 (82% identical), mouse Stab1 (82% identical), pig STAB1 (82% identical), rat Stab1 (81% identical), zebrafish stab1 (40% identical), tropical clawed frog STAB1 (28% identical). Paralogues in human: STAB2 (40% identical), TNFAIP6 (3% identical).
Diseases named in the same sentence as STAB1 in open-access papers:
STAB1 is named in the same sentence as 90 diseases in open-access papers, as found by Europe PMC text mining. Sharing a sentence is not in itself a finding about the gene and the disease. The quoted sentences say what the papers report.
breast cancer (19 papers, 2016 to 2025). A primary or metastatic malignant neoplasm involving the breast. "In a murine breast cancer model, stabilin-1 was able to promote tumor growth, and this function was linked to the stabilin-1-mediated scavenging of SPARC." (PMID 39516356, 2024). "STAB1 is expressed on tumor‐associated macrophages in several cancers, and in human breast cancer STAB1 was found in stage I and IV disease, suggesting a role in early primary tumor growth and progression." (PMID 36617746, 2023). "ARHGDIB and STAT1 are increased in models of breast cancer CTCs while STAB1 and TLR2 are increased in tumor-associated inflammatory cells in breast and colorectal cancer." (PMID 36176417, 2022). "In accordance with our results, the previous studies have also shown that a high density of tumor-infiltrating stabilin-1+ Mφs is associated with worse prognosis in colorectal and breast cancers." (PMID 31302753, 2020). "Furthermore, a high density of tumor-infiltrating stabilin-1+ Mφs is associated with adverse patient outcomes in breast cancer and colorectal carcinoma." (PMID 31302753, 2020). "Accumulating evidence has shown that high STAB1 expression correlates with poor prognosis in several cancers, including breast cancer, oral cancer, gastric cancer, hematological malignancies, and metastatic colorectal cancer (CRC)." (PMID 41007347, 2025). "Studies have shown high STAB1 expression in lymphatic vessels of squamous cell cancer of the head and neck, as well as breast cancer." (PMID 41007347, 2025). "STAB1+ macrophages are considered pro-tumorigenic, facilitating tumor cell proliferation by suppressing immune responses in breast cancer." (PMID 41007347, 2025). "Last, ligands of Stab1 also influence cancer progression as SPARC inhibits metastasis of breast cancer cells or reduces the growth of neuroblastoma, Lewis lung carcinoma, or EL4 cells." (PMID 38275881, 2024). "STAB1+ macrophages have additionally been found in samples from human breast cancer patients, and the effects of STAB+ expression on patient outcome were stratified based on localization within the tumor." (PMID 38426622, 2024). "This is supported by a study in human breast cancer patients that demonstrated only a very mild infiltration by STAB1+ cells in the liver." (PMID 38275881, 2024). "STAB1+ macrophages have been identified in both mouse models and human breast cancer patients, and injection of TS/A mammary adenocarcinoma cells into STAB1−/− mice is associated with reduced tumor growth." (PMID 38426622, 2024). "TAM-expressed stabilin-1 mediates clearance of tumor growth-inhibiting factor SPARC in a mouse model of breast cancer, and germinal knock-out of stabilin-1 results in the statistically significant reduction of primary tumor growth in this model." (PMID 36686729, 2022). "YKL-39 was identified as a biomarker for specific stabilin-1+ TAM subpopulation in human breast cancer." (PMID 34209679, 2021). "In the study of STAB1 expression on TAM in breast cancer, some scholars found that STAB1-mediated silencing of extracellular tumor growth suppressor was the mechanism of STAB1-induced tumor growth." (PMID 33748290, 2021). "On the other hand, the amount of stabilin-1+ (M2 marker) TAMs in human breast cancer was mostly abundant on stage I disease." (PMID 33194645, 2020). "Abundant expression of stabilin-1 in human breast cancer prompted us to examine its role in the regulation of primary breast tumor growth in a mouse model with genetic ablation of stabilin-1." (PMID 27105498, 2016). "In conclusion, our data demonstrate abundant expression of stabilin-1 in human breast cancer and reveal its importance for tumor growth in mouse breast cancer model." (PMID 27105498, 2016). "Of note, expression of stabilin-1 in human breast cancer was most intensive in stage I and IV disease suggesting its crucial role for early primary tumor growth and progression." (PMID 27105498, 2016).
breast cancer (continued). "In the current study we demonstrate the expression of scavenger receptor stabilin-1 on TAM in human breast cancer and reveal its tumor-promoting role using stabilin-1 ko breast cancer mouse model." (PMID 27105498, 2016). "Overall, our data indicated that stabilin-1 is expressed in human breast cancer with prevalent localization on TAM, and marks distinct subpopulation of cells in the tumor stroma with decreased or absent expression of CD68." (PMID 27105498, 2016). "Here, we demonstrate that stabilin-1 is expressed on TAM in human breast cancer, and its expression is most pronounced on stage I disease." (PMID 27105498, 2016). "Collectively, these studies demonstrate that macrophages expressing LYVE‐1 and associated markers (PDPN, TIM4, STAB1, and FOLR2) may have key roles in the context of breast cancer." (PMID 38426622, 2024). "Despite its tumor-promoting role in mouse models of melanoma and lymphoma the expression and functional role of stabilin-1 in breast cancer was unknown." (PMID 27105498, 2016). "Six of the genes (CASP1, CCL2, ADGRE5, IL3RA, RSPO1, and STAB1) are co‐expressed with the CH25H gene in both cancers, while two genes (ANPEP in breast cancer and CCL8 in prostate cancer) are exclusively co‐expressed with the CH25H gene in one of the tumors." (PMID 41159143, 2025). "In this study for the first time we show that stabilin-1 is a specific scavenger receptor for EGF, a growth factor critical for progression of breast cancer." (PMID 36960065, 2023). "In breast cancer, TAMs are represented by phenotypes, expressing the variety of scavenger receptors (CD163, CD204, CD206 and stabilin-1)." (PMID 36960065, 2023). "In a breast cancer spheroid mouse model infiltrated with HIF-1α−/− macrophages, the amount of CD206+ and stabilin-1+ macrophages was significantly increased compared to spheroids infiltrated by WT macrophages." (PMID 34209679, 2021). "Recent work has highlighted stabilin-1 upregulaton in TAMs in a range of cancers, and in an in vivo model of breast cancer the uptake of SPARC, a tumour inhibiting factor, by stabilin-1 on TAMs promoted tumor progression." (PMID 31315308, 2019). "By immunohistochemistry we found that stabilin-1 is expressed in a significant subset of TAM in patients with breast carcinoma, and its expression is higher during early stage of breast cancer progression (stage I) and in case of metastatic cancer (stage IV)." (PMID 27105498, 2016). "Here we examined whether stabilin-1 can mediate clearance of EGF, an essential growth factor that promotes breast cancer progression." (PMID 36960065, 2023). "In breast cancer stabilin-1 is predominantly expressed on TAMs, and not on other cells types (like lymphatic, angiogenic or sinusoidal endothelial cells)." (PMID 36960065, 2023). "In human breast cancer, we found that stabilin-1+ TAMs but neither cancer cells, nor endothelial cells or fibroblasts express YKL-39." (PMID 34209679, 2021). "Immunofluorescent/confocal microscopy analysis of distribution of CD68 and stabilin-1 in human breast cancer samples of all stages demonstrated presence of three cell subpopulations: CD68+Stab-1−, CD68−Stab-1+, and CD68+Stab-1+." (PMID 27105498, 2016). "Since stabilin-1 expression was found on intratumoral vessels in human urothelial bladder cancer and melanoma we have analysed co-expression of stabilin-1 with vascular markers CD34 and CD31 in human breast cancer." (PMID 27105498, 2016). "Stabilin-1 mediates phagocytosis of “unwanted-self” components, intracellular sorting, and endocytic clearance of extracellular ligands including SPARC that modulates breast cancer growth." (PMID 27105498, 2016). "Since stabilin-1 was identified by us and others as a marker for alternative macrophage activation in rodents and human, we first investigated its expression on TAM in tissue sections from patients with breast cancer using quantitative IHC and confocal microscopy." (PMID 27105498, 2016).
melanoma (9 papers, 2016 to 2025). A malignant, usually aggressive tumor composed of atypical, neoplastic melanocytes. "Altogether, the establishment and progression of melanoma liver colonization were only mildly altered by Stab1 deficiency, as liver metastases of B16F10 luc2 tended to be smaller in Stab1 KO." (PMID 38275881, 2024). "In tumor bearing, Stab1 deficient mice an accumulation of POSTN was predominantly seen in the matrix of Wt31 melanoma metastases (p = 0.0159)." (PMID 38275881, 2024). "Stabilin-1 is expressed in vivo in tumor-associated macrophages (TAM) in mouse models of melanoma, pancreatic insulinoma and glioblastoma." (PMID 27105498, 2016). "Finally, another in vivo study using a STAB1-deficient mouse model for hepatic melanoma metastasis revealed that STAB1 modulates the deposition of ECM components, specifically POSTN and TGFβ1, which regulate immune cell infiltration and tumor growth." (PMID 41007347, 2025). "Deficiency of Stab1 on hepatic endothelial cells could affect the pattern of hepatic melanoma metastasis or the development and maturation of its vasculatures." (PMID 38275881, 2024). "In addition, growth and lymph node metastasis of subcutaneous B16F10 melanomas are significantly reduced by genetic deficiency of Stab1 or targeting with an anti-Stab1 antibody in a mouse model." (PMID 38275881, 2024). "In the context of melanoma tumor development, preclinical studies using Stab1 KO mice have brought forth the following valuable information." (PMID 41007347, 2025). "Hepatic metastases of both Wt31 and B16F10 luc2 melanoma showed a pushing type histopathological growth pattern in Stab1 KO and Ctrl." (PMID 38275881, 2024). "The number of liver metastases was similar between Stab1 KO and Ctrl after i.v. injection of Wt31 melanoma cells." (PMID 38275881, 2024). "The growth of subcutaneous B16 melanomas is significantly reduced by a global knockout (KO) of Stab1." (PMID 38275881, 2024). "As Stab1 is being investigated as a target in multiple different cancers, such as melanoma, we decided to investigate its impact on hepatic melanoma metastasis." (PMID 38275881, 2024). "Since Stab1 mediates the adhesion of multiple cell types and even promotes lymph node metastasis of melanoma, initial tumor cell adhesion and retention to the liver were studied by BLI." (PMID 38275881, 2024). "Upregulation of genes involved in macrophage recruitment (Ccl2), cell adhesion and migration (Vcam1, Stab1, Lyve1), angiogenesis (Vegfa) and cell proliferation/survival (Igf1) all suggested a phenotype similar to TAMs of s.c. melanoma." (PMID 36241867, 2022). "In summary, we found that NOTCH3, DBN1, KDELC2, and STAB1 were closely related to M2 macrophage infiltration in melanoma tissues." (PMID 33748290, 2021). "STAB1 was considered in this paper to have a strong positive correlation with M2 macrophages in melanoma." (PMID 33748290, 2021). "The yellow-green module was the coexpression module most related to M2 macrophages in TCGA-SKCM; NOTCH3, DBN1, KDELC2, and STAB1 were identified as the essential genes that promoted the infiltration of M2 macrophages in melanoma." (PMID 33748290, 2021). "The expression of stabilin-1 was found on tumor-associated macrophages (TAM) in mouse and human cancers including melanoma, lymphoma, glioblastoma, and pancreatic insulinoma." (PMID 27105498, 2016). "We found that in murine B16F1 melanoma tumor model stabilin-1 is expressed on a subset of CD11b(+), F4/80(+) tissue macrophages predominantly on the tumor periphery, while only single stabilin-1+ macrophages have been detected inside tumor mass." (PMID 27105498, 2016). "Recently, Karikoski and colleagues demonstrated tumor-promoting role of stabilin-1 in mouse models of B16 melanoma and EL-4 lymphoma." (PMID 27105498, 2016). "Also, STAB1 was found to be expressed in cutaneous T-cell lymphoma, melanoma metastasis, and chronic inflammation of the skin, such as psoriasis." (PMID 41007347, 2025).
melanoma (continued). "Detailed analyses of the hepatic microenvironment after melanoma colonization revealed an altered deposition of Stabilin ligands which could also mask potential beneficial effects of targeting Stab1." (PMID 38275881, 2024). "In this study, we investigated whether the targeting of Stab1 might also influence melanoma liver colonization, as hepatic metastasis of melanoma is well described as a poor prognostic factor." (PMID 38275881, 2024). "In contrast, loss of Stab1 did not result in altered melanoma liver colonization in our study, as the numbers of liver metastases were similar in Stab1 KO and Ctrl after i.v. injection of Wt31 or spleen injection of B16F10 luc2." (PMID 38275881, 2024). "As treatment with anti-Stab1 antibodies also decreases both the growth and metastasis of B16 melanoma and EL-4 lymphoma, this strategy might be used therapeutically." (PMID 38275881, 2024). "This study investigated whether targeting of Stab1 might also influence melanoma liver colonization, as hepatic metastasis of melanoma is a poor prognostic factor." (PMID 38275881, 2024). "In a second model, B16F10 luc2 melanoma cells were injected into the spleen of Stab1 KO and Ctrl." (PMID 38275881, 2024). "In these studies, we demonstrated the role of NOTCH3, DBN1, KDELC2, and STAB1 in melanoma patients." (PMID 33748290, 2021). "STAB1 was also a poor prognostic factor in AML, and the oncogenic functions have been confirmed in melanoma." (PMID 38322990, 2024). "The expression of STAB1 was found on the TAM of melanoma, and it can promote the tumor in the mouse model of melanoma." (PMID 33748290, 2021). "First, studies have shown that the absence of STAB1 results in decreased tumor size in primary melanoma tumors compared to wildtype animals." (PMID 41007347, 2025). "This indicates that Stab1 does not impair or mediate tumor cell adhesion and retention to the hepatic sinusoids in this melanoma model." (PMID 38275881, 2024). "Despite promising results of anti-Stab1 treatments in different tumors and organs, hepatic melanoma metastasis was not directly affected in two melanoma models." (PMID 38275881, 2024). "In two models of hepatic melanoma metastasis, no direct influence of anti-Stab1 treatment was found." (PMID 38275881, 2024). "Additionally, preclinical studies using Stab1 KO mice confirmed that the absence of STAB1+ TAMs resulted in reduced tumor burden of several cancers, including melanoma, lung adenocarcinoma, medullary mammary adenocarcinoma, and lymphoma." (PMID 41007347, 2025). "However, a tendency towards smaller metastases of B16F10 luc2 (p = 0.0635), but not Wt31 melanoma, was observed in Stab1 KO as compared to Ctrl." (PMID 38275881, 2024). "Upon liver colonization with Wt31 melanoma, the levels of both CD4+ and CD8+ decreased in the liver, but no statistical differences between Stab1 KO and Ctrl were detected." (PMID 38275881, 2024).